UQCRC1 (ubiquinol-cytochrome c reductase core protein 1)
Diseases named in the same sentence as UQCRC1 in open-access papers (continued):
Sharing a sentence is not in itself a finding about the gene and the disease.
xerostomia (1 paper, 2025). Dryness of the mouth resulting from reduced salivary secretion. "Ubiquinol-cytochrome c reductase core protein 1 (encoded by UQCRC1) is an additional protein downregulated in the right parotid, highlighting mitochondrial dysfunction to neurodegenerative diseases in relation to xerostomia." (PMID 40806170, 2025). "The downregulation of key proteins involved in oxidative stress and neurodegenerative diseases, encoded by PARK7, GLO1, GLUD2, VDAC2, UQCRC1, and UNC5C, including the 20S proteasome core complex proteins, highlights a possible mechanistic link to xerostomia pathophysiology." (PMID 40806170, 2025). "Akin to VDAC2, UQCRC1 emphasizes mitochondrial dysregulation to the progression of neurodegenerative diseases through dopaminergic neuronal degeneration, possibly related to the development of xerostomia." (PMID 40806170, 2025).
tumor (12 papers, 2012 to 2025). "Our results suggest that reduced expression of UQCRC1 is associated with tumor progression." (PMID 27941907, 2016). "We demonstrated the reduced chemotaxis and cytotoxicity of NK cells toward PC cells or tumor spheroids overexpressing UQCRC1 by in vitro co-culture." (PMID 35769718, 2022). "UQCRC1 overexpression accelerated the tumor growth in untreated mice (p < 0.01), and NK cell therapy delayed the tumor growth of both UQCRC1-overexpressing and control tumors (p < 0.001)." (PMID 35769718, 2022). "As expected, NK cell-mediated apoptosis of tumor cells was markedly decreased in UQCRC1-overexpressing PANC-1 spheroids compared to control spheroids (19.66 ± 1.75% vs 27.17 ± 2.80%, p < 0.05)." (PMID 35769718, 2022). "In this study, we report, for the first time, that upregulation of UQCRC1 in PC cells can indeed impair the cytotoxicity and migration of NK cells by generating extra eATP, thereby promoting tumor progression." (PMID 35769718, 2022). "As UQCRC1 expression is shown to be upregulated in approximately 72% of tumor tissues, our study suggests UQCRC1 as a new molecular target for PDAC intervention." (PMID 32089737, 2020). "Consistent with our in vitro findings, UQCRC1 overexpression significantly increased the tumor burden in both subcutaneous (0.49 ± 0.08 g vs. 0.79 ± 0.11 g, P < 0.05) and orthotopic (0.48 ± 0.05 g vs. 0.90± 0.07 g, P < 0.001) mouse models of PDAC." (PMID 32089737, 2020). "To date, the mechanistic studies of UQCRC1 in tumors only focused on the tumor cells themselves." (PMID 35769718, 2022). "However, compared to control xenografts, UQCRC1-overexpressing xenografts responded worse to adoptive NK cell therapy, as reflected by the decreased tumor inhibition rate (p < 0.05)." (PMID 35769718, 2022). "However, besides promoting the proliferation of PC cells by increasing the amount of extracellular ATP (eATP), whether UQCRC1 can promote tumor growth in other pathways remains unknown." (PMID 35769718, 2022). "In conclusion, GP5, CCT7, UQCRC1, PGD, GAPDH and LDHA have been found to play a role in tumor development, prognosis and even diagnosis in previous studies." (PMID 36404333, 2022). "Mice bear tumors developed from UQCRC1-overexpressing or control PANC-1 cells were peritumorally injected with NK-92MI cells and tumor growth was monitored." (PMID 35769718, 2022). "In order to clarify which mutant is responsible for anti-tumor property of AVN A, we compared the expression of NDUFS2 and UQCRC1 in DDX3 mutant cell lines." (PMID 31391454, 2019). "Immunohistochemical analysis of tumor tissues revealed that Liensinine treatment led to a marked reduction in the expression levels of HK2, PDK1, and HIF-1α, while increasing the expression of IDH3B, UQCRC1, and phosphorylated AMPK (P-AMPK)." (PMID 40665352, 2025). "Extracellular Ado (eAdo) accumulation may result from elevated eATP levels as well as increased expression of CD39 and CD73, two major ectonucleotidases for eATP hydrolysis, to varying degrees in UQCRC1-overexpressing PANC-1 cells and tumor xenografts." (PMID 35769718, 2022). "Thus, UQCRC1 and UQCRFS1 seem to be involved in carcinogenesis, but deregulation may be depending upon the tumor entity, and its expression is decreased in ccRCC." (PMID 27845902, 2016).
cancer (10 papers, 2013 to 2025). A tumor composed of atypical neoplastic, often pleomorphic cells that invade other tissues. "Altogether, both in vitro and in vivo findings demonstrate that UQCRC1 upregulation in cancer cells inhibits NK cell-mediated cytotoxicity against PC." (PMID 35769718, 2022). "Dysregulation of UQCRC1 has been reported in neuropsychic diseases, metabolic disorders, and several cancers." (PMID 35769718, 2022). "In the current study, we investigated, for the first time, the biological impact of the mitochondrial protein UQCRC1 in cancer." (PMID 32089737, 2020). "Low mRNA levels UQCRC1 were also correlated with a shorter period of cancer-specific and overall survival." (PMID 27845902, 2016). "Mechanistically, we found the UQCRC1/eATP axis reduced the expression of chemokine CCL5 in cancer cells and altered the balance of activating receptor DNAM-1 and inhibitory receptor CD96 on NK-92MI cells, resulting in decreased chemotaxis and exhausted phenotype of NK-92MI cells." (PMID 35769718, 2022). "The abnormal expression of UQCRC1 has been reported in various human cancers." (PMID 35769718, 2022). "Analyzing gene expression and DNA methylation in The Cancer Genome Atlas cohort revealed an inverse correlation of gene expression and DNA methylation, suggesting that DNA hypermethylation is regulating the expression of UQCRC1 and UQCRFS1." (PMID 27845902, 2016). "Up-regulation of UQCRC1 might contribute to the rapid proliferation of cancer cells by increased synthesis of ATP." (PMID 23880933, 2013). "This suggests that the anti-cancer effects of sinulariolide may be correlated with mitochondrial function in A375 cells and associated with the reduction of IDH and UQCRC1 and enhancement of prohibitin." (PMID 23880933, 2013). "Therefore, we assumed that the oncogenic effect of UQCRC1 in PC may be generated not only through its direct impact on cancer cell growth, but also through its modulatory impact on NK cell repertoire in the TME." (PMID 35769718, 2022).
neurodegenerative disease (3 papers, 2015 to 2025). A disorder of the central nervous system characterized by gradual and progressive loss of neural tissue and neurologic function. "An important property of the neurodegenerative diseases is the downregulated oxidative phosphorylation because of the dysfunctional brain mitochondria and the varied genes including UQCRC1, UQCR10, SDHB, ATP5B, ATP5C1, NFUFA1, and VDAC1." (PMID 29359159, 2017).
metabolic disease (2 papers, 2015 to 2020). A congenital disorder (due to inherited enzyme abnormality) or acquired (due to failure of a metabolically important organ) disorder resulting from an abnormal metabolic process. "Previously, dysregulation of UQCRC1 was reported to be associated with several disorders, including metabolic diseases 23, neuropsychic diseases 30, and reproductive system diseases." (PMID 32089737, 2020). "Recent reports have studied the activity and abundance of UQCRC1 in the context of different metabolic diseases." (PMID 26121299, 2015).
musculoskeletal diseases (1 paper, 2022). "Muscle disuse and musculoskeletal diseases are both linked with mitochondrial protein expression changes, including UQCRC1 dysregulation." (PMID 35788655, 2022).
UQCRC1 also shares sentences with these, for which no sentence is quoted: breast carcinoma (3 papers); clear cell renal cell carcinoma (3); diabetes (3); cardiomyopathies (2); Parkinson’s (2); adenoma (1); colon tumor (1); dementia (1); epilepsy (1); Fanconi anemia (1); gastric cardia carcinoma (1); genetic disorder (1); hearing loss (1); hypertrophic cardiomyopathy (1); infection (1); liver fibrosis (1); major depressive disorder (1); metastatic tumors (1); non-small cell lung carcinoma (1); ovarian adeno-carcinomas (1); reproductive system diseases (1); type 2 diabetes (1).